RN7SKP278 (RN7SK pseudogene 278)
Gene: Miscellaneous RNA gene on chromosome 10 (108,940,969 to 108,941,310, reverse strand). Ensembl gene ENSG00000222436.
Homologues: Orthologues: chimpanzee 7SK (94% identical). Paralogues in human: RN7SKP79 (66% identical), RN7SKP3 (65% identical), RN7SKP90 (65% identical), RN7SKP217 (65% identical), RN7SKP250 (65% identical), RN7SKP180 (65% identical), 7SK (64% identical), RN7SKP127 (64% identical), RN7SKP184 (64% identical), RN7SKP245 (64% identical), RN7SKP124 (64% identical), RN7SKP71 (63% identical), and 283 more.